DSEL (dermatan sulfate epimerase like)
Synonyms: C18orf4; NCAG1; FLJ11477; DE-epi2
Tractability: Antibody: UniProt predicts a signal peptide or a membrane-spanning region; the Human Protein Atlas places it where antibodies can reach.
Gene: Protein-coding gene on chromosome 18 (67,506,587 to 67,516,723, reverse strand). Ensembl gene ENSG00000171451.
Subcellular location: Membrane
Subcellular location (Human Protein Atlas): Plasma membrane; Nucleoplasm
Pathways (Reactome):
Metabolism: DS-GAG biosynthesis
Gene Ontology:
Molecular function: chondroitin-glucuronate 5-epimerase activity; sulfotransferase activity
Biological process: chondroitin sulfate proteoglycan metabolic process; dermatan sulfate proteoglycan biosynthetic process; dermatan sulfate proteoglycan metabolic process
Cellular component: Golgi membrane; membrane
Genetic constraint (gnomAD): Loss-of-function variants: 61 observed, 101.6 expected, observed/expected ratio (o/e) 0.6, 90% interval 0.49 to 0.74. The upper end of that interval is the gene's LOEUF score, 0.74, which puts it in group 3 of 6, group 1 being the genes least tolerant of losing a copy. Missense variants: 1,320 observed, 1,507.9 expected, observed/expected ratio (o/e) 0.88, 90% interval 0.84 to 0.92. Synonymous variants: 514 observed, 530.06 expected, observed/expected ratio (o/e) 0.97, 90% interval 0.9 to 1.04.
Homologues: Orthologues: chimpanzee DSEL (99% identical), macaque DSEL (99% identical), rabbit DSEL (95% identical), dog DSEL (95% identical), pig DSEL (93% identical), mouse Dsel (89% identical), rat Dsel (88% identical), guinea pig DSEL (77% identical), tropical clawed frog dsel (70% identical), zebrafish dsela (57% identical). Paralogues in human: DSE (31% identical).
Diseases named in the same sentence as DSEL in open-access papers:
DSEL is named in the same sentence as 8 diseases in open-access papers, as found by Europe PMC text mining. Sharing a sentence is not in itself a finding about the gene and the disease. The quoted sentences say what the papers report.
bipolar disorder (4 papers, 2018 to 2023). A disorder of the brain that causes unusual shifts in mood, energy, activity levels and the ability to carry out day-to-day tasks. "Human DSEL (C18orf4) has been genetically linked to bipolar disorder and early-onset major depressive disorder." (PMID 29370293, 2018). "Thus, further behavioral analyses are needed, such as an open-field test, a separation-reunion test, resident-intruder test, and social dominant tube test, in order to explore the functions of DS in the brain, since it has been reported that various mutations in DSEL cause bipolar disorder." (PMID 35806490, 2022). "A bipolar disorder was caused by a variety of homozygous and heterozygous variants in DSEL including the substitution of a nucleotide in the 5′-non-coding region, p.Val287Ile, p.Pro673Ser, p.Tyr730Cys, p.Pro942Ser, and p.Ile1113Met." (PMID 35806490, 2022). "Two non-synonymous mutations in the coding region of DSEL (Y730C, I1113M) were reported in a heterozygous state in 3 individuals from a group of 113 bipolar disorder patients, but not in the control group." (PMID 29370293, 2018). "It should be noted that DSE is identical to SART2 (squamous cell carcinoma antigen recognized by T cells 2), which encodes a protein with unknown function highly expressed in cancer cells and tissues, and that DSEL is identical to C18orf4, which is a candidate gene for a bipolar disorder." (PMID 36833436, 2023).
glioma (2 papers, 2018 to 2024). A benign or malignant brain and spinal cord tumor that arises from glial cells (astrocytes, oligodendrocytes, ependymal cells). "Furthermore, a search of the REpository for Molecular BRAin Neoplasia DaTa (REMBRANDT) database revealed that high expression of DSE is associated with worse overall survival in glioma patients (n = 329), whereas DSEL expression does not correlate with patient outcomes." (PMID 29864158, 2018). "Similarly, another model for predicting the prognosis of lower-grade gliomas, which is based on four RNA-edited sites (PRKCSH chr19:11561032, DSEL chr18:65174489, UGGT1 chr2:128952084, and SOD2 chr6:160101723), also reported an AUC of 0.823." (PMID 39764127, 2024).
squamous cell carcinoma (1 paper, 2017). A carcinoma arising from squamous epithelial cells. "DSEL (synonym: C18orf4) which encodes the dermatan sulfate epimerase-like protein that shows a significant homology with DSEP (synonym: SART-2), a squamous cell carcinoma antigen that can induce HLA-24-restricted and tumor-specific cytotoxic T-lymphocytes." (PMID 28157713, 2017).
tumor (5 papers, 2017 to 2024). "DSEL (dermatan sulfate epimerase-like) is implicated in D-glucuronic acid metabolism and tumor rejection." (PMID 34035245, 2021). "DSEL, ID4, REEP2, and TMSB15A were upregulated in the NPC samples compared with the non-tumor samples." (PMID 38532632, 2024). "Compared to non-tumor samples, REEP2, TMSB15A, DSEL, and ID4 were upregulated in NPC samples." (PMID 38532632, 2024). "However, the expression of DSEL, ID4, REEP2, and TMSB15A not related the tumor progression." (PMID 38532632, 2024).
DSEL also shares sentences with these, for which no sentence is quoted: cancer (3 papers); depression (2); diaphragmatic hernia (1); microphthalmia (1).